IL27 (interleukin 27)
Diseases named in the same sentence as IL27 in open-access papers (continued):
Sharing a sentence is not in itself a finding about the gene and the disease.
tumor (continued). "Thus, analysis on the role of physiological IL-27 signaling on endogenously arising tumors is paramount to properly assess the anti-tumor potential of this cytokine." (PMID 23554861, 2013). "IL-27 has also been shown to enhance IL-10 production and negatively regulate IL-4 and IL-17, however, subtle effects of Il27ra genotype were observed for these cytokines in the tumor models." (PMID 23554861, 2013). "However, the role of IL-27 in immunity against tumors that develop in situ and in tumor immunosurveillance remain undefined." (PMID 23554861, 2013). "Despite this, evidence from tumor cell line transfer models suggested that IL-27 could promote immune responses in the tumor context." (PMID 23554861, 2013). "Indeed, while 15/28 (54%) of IL-27-positive cases were also positive for PD-L1 in tumor cells, only 2/12 (17%) of IL-27-negative cases stained positive for PD-L1 (p<0.05)." (PMID 24130734, 2013). "Recent studies also confirmed that IL-27 has anti-tumor effects." (PMID 22827855, 2012). "An increase in tumor growth rates in WSX1-positive tumors compared to the cognate controls in TCCR−/− mice (IL27 cannot signal in this host) suggests that WSX1 expression in tumors does not act as a decoy receptor for IL27 but rather promotes tumor growth via an alternate mechanism." (PMID 21559505, 2011). "Our previous data suggested that WSX1 inhibited tumor growth independently of IL27 signaling." (PMID 21559505, 2011). "IL-27 can stimulate cytotoxic T-cell activity and may play a role in tumor immunotherapy." (PMID 40519922, 2025). "Additionally, elevated TNF-α and IL-27 levels reflect abnormal immune activation and dysregulated cytokine production, which may contribute to tumor growth, immune evasion, or disease progression." (PMID 41254398, 2025). "Additionally, IL-27 may exert broader immunosuppressive effects on the anti-tumour response than those described here." (PMID 41296385, 2025). "However, anti-tumor immunity is rarely achieved through the activity of only IL-27." (PMID 39063193, 2024). "In addition, IL-6 and IL-27 are also important cytokines that upregulate co-inhibitory signals on tumor-infiltrating T cells, correlating with T cell exhaustion in both human and mouse tumor models." (PMID 37398674, 2023). "On the basis that I-TAC, C5/C5a, IL-6, CD54, and IL-27 are the cytokines related to the immune system, we conclude that the KUP system acts as ROS photogenerators and induces the immune activity to control the release of cytokines, which cause the tumor eradication." (PMID 36932086, 2023). "Overall, the IL-27+cabo combination therapy appeared to increase the infiltration of pro-inflammatory and anti-tumor immune effectors that could exert an anti-tumorigenic effect, decrease the presence of regulatory immune cells, and potentially inhibit angiogenesis within the tumor microenvironment." (PMID 37842640, 2023). "IL-27 is a cytokine that belongs to the IL-12 superfamily, which comprises IL-12, IL-23 and IL-35, which are produced by antigen-presenting cells in response to microbial or host immune stimuli and are involved in the regulation of immune responses against infections and tumor development." (PMID 36362718, 2022). "Recently, novel lipid nanoparticles (LNPs) encapsulated with mRNAs encoding cytokines including IL-12, IL-27 and GM-CSF were designed to elucidate a synergistic effect in suppressing tumor growth but not causing adverse reactions compared to GM-CSF or IL-27 mRNAs in monotherapy strategies." (PMID 36428682, 2022). "However, the presence of IL-27 during the initial vaccination may help promote innate immune cell activation to establish strong anti-tumor responses." (PMID 35529885, 2022). "Therefore, both IFN-γ and IL-27 induce immune-regulatory circuits, which may limit anti-tumor immunity." (PMID 34439164, 2021). "In addition, the DC-derived cytokine IL27 can exert anti-tumor activity by activating NK cells." (PMID 33868261, 2021).
tumor (continued). "Considering that bulk RNA sequencing measures the mRNA expression of the entire tumor tissue, which includes tumor cells, stromal cells, immune cells, and some extracellular cytokines, we speculated that IL27 could promote programmed cell death of tumor cells by enhancing effector immune cells." (PMID 34733272, 2021). "We hypothesized that addition of IL-18, which can induce the proliferation of several immune effector cells through inducing IFNγ, major histocompatibility complex (MHC) class I expression, and also by inhibiting angiogenesis, could synergize with IL-27 to enhance tumor growth control." (PMID 34209203, 2021). "Therefore, in this work, we tested if directly injecting AAV-IL-27 into tumors could lead to similar anti-tumor effect yet avoiding uncontrolled IL-27 production." (PMID 32292786, 2020). "Therefore, it is possible that the addition of IL-27 alongside STAT3 inhibitors may serve to further enhance their efficacy, as inhibition of STAT3 could favor STAT1-dominant signaling, promoting the anti-tumor capacity of IL-27." (PMID 31681561, 2019). "Also, the impact of IL-27 on tumor development revealed divergent effects." (PMID 31637217, 2019). "However, a tumor-promoting role of IL-27 has also been proposed." (PMID 31637217, 2019). "Furthermore, IL-27 enhances anti-tumor CD8+ T cell survival." (PMID 31681561, 2019). "Moreover, akin to depleting DC, targeting IL-27 and iNOS were tumor protective in PDA and abrogated many elements of the characteristic CD4+ T-cell Tr1-like surface phenotype and cytokine profile in the TME, although mechanistic links to specific DCs subsest remains to be defined in vivo." (PMID 30926808, 2019). "Moreover, IL-27 can enhance cytotoxic anti-tumor responses of CD8+ T cells and NK cells, and therefore may be used to advance current T cell and NK cell therapies." (PMID 31681561, 2019). "Moreover, IL-27 can influence the availability of IL-35 and thus may affect the outcome of tumor survival and metastasis." (PMID 31681561, 2019). "Besides its direct inhibitory activity on tumor cells, IL-27 may also exert indirect antitumor effects by targeting the tumor microenvironment." (PMID 28255204, 2017). "Therefore, IL-27 may have a dual role in anti-tumor immunity and shares several immune-regulatory functions with IFN-γ, in relationship to the common usage of the STAT1 intracellular signaling pathway." (PMID 29020964, 2017). "Notably, during anti-tumor immune responses IL-27 may act earlier than IFN-γ, being a cytokine produced by innate cells such as macrophages and DC." (PMID 28456791, 2017). "Besides the activity on tumor cells, IL-27 may also induce an immune-regulatory phenotype in tumor-associated macrophages through upregulation of CD39 or PD-L1." (PMID 28255204, 2017). "Indeed, our data provide new evidence that, beyond its well known anti-tumor effects, IL-27 may also elicit immune-regulatory circuits, particularly in the tumor environment, through the induction of PD-L1 and/or IDO in EOC cells and monocytes." (PMID 26657115, 2015). "Moreover, IL-27 dose-dependently inhibited their tumor growth." (PMID 24155891, 2013). "Thus, it is conceivable that IL-27 produced by tumor cells could contribute to IL-10 induction in an autocrine manner, in some cases." (PMID 24130734, 2013). "In addition, loss of IL-27 signaling results in reduced production of IFN-γ by CD4+ T cells and enhanced generation of regulatory T cells, effects which can inhibit an effective anti-tumor response." (PMID 23554861, 2013). "Similarly, IL27 plays a role not only in tumor growth but also in metastasis." (PMID 21559505, 2011). "Therefore, tenascin could represent an interesting target for tumor-delivery of IL-12 and IL-27 in PC." (PMID 19798410, 2009). "IL11 (p = 0.010), IL23A (p = 1.77e − 05), IL27 (p = 1e − 05) and IL32 (p = 0.001) exhibited significant correlations with tumor stage." (PMID 40612864, 2025).
tumor (continued). "IL-27 can induce the high expression of IDO in tumor cells, which is related to tumor immune escape." (PMID 40642057, 2025). "Nevertheless, our design was guided by earlier studies reporting decreased IL-27 levels in CLL patients, which had been interpreted as suggestive of an anti-tumour role for this cytokinę." (PMID 41296385, 2025). "Integrating engineered mouse models with molecular studies and functional experiments, the authors solved this apparent paradox, and proved the essential role of IL-27 in CTL infiltration, fitness, and tumor control." (PMID 40254608, 2025). "In a murine melanoma model, administration of IL-27-neutralizing antibodies significantly reduced IFN-γ production by T-lymphocytes in both lymph nodes and the tumor." (PMID 40725022, 2025). "The expression levels of IL11, IL23A, IL27, and IL32 were significantly correlated with tumor stage." (PMID 40612864, 2025). "Among the mechanisms that regulate PD-L1 expression, the production of cytokines, such as IL-1a, IL-27, IL-10, and IL-32g, in the tumor microenvironment (TME) can upregulate the expression of PD-L1 on monocytes and tumor cells." (PMID 38543183, 2024). "In the flow cytometry assay, the expression of IL-21, IL-27, and IFNA2 proteins with anti-tumor functions were elevated significantly in DBMSCs after treatment with MDA231 cells compared to the untreated DBMSCs." (PMID 39768220, 2024). "Despite this, there was evidence of anti‐tumor activity such as the low number of CD163+ cells, greater necrosis, high levels of IL‐10 and low levels of IL‐6 and IL‐27." (PMID 38600057, 2024). "IL-27 exerts many of its anti-tumor effects via STAT1 mediated signaling, indicating that the delivered IL-27 is bioactive." (PMID 37842640, 2023). "IL-27 stimulates multiple lineages of immune cells, and IL-27-induced C–C motif ligand 5 (CCL5) contributes to IL-27 mediated anti-tumor activity." (PMID 37805495, 2023). "A PPI network of the selected 18 genes was constructed based on the STRING database, indicating the broad functional overlap between IL27 and IFN-γ, and interaction in remodeling the tumor immune microenvironment between IFN-γ and HGF." (PMID 36713514, 2022). "Significantly increased concentration of CXCL16, IL-27, IFN-γ, and IL-17 and decreased concentration of immunosuppressive TGF-β and IL-10 were measured in serum samples and tumor tissues of 4T1+d-MAPPS-treated mice." (PMID 35757015, 2022). "Meanwhile, IL27 is known to exert dual roles in the TME, as it can induce effector immune response as well as stimulate tumor expansion by suppressing immune function." (PMID 34733272, 2021). "Finally, since multiple soluble mediators, such as TNF-α, IFN-γ, IL-1β, IL-17, and IL-27, induce PD-L1 expression on tumor cells, it may be reasonable to raise the question of whether the expression of certain mediators among them is downregulated by NDRG2 expression." (PMID 34885221, 2021). "Levels of IL-9 and IL-27 were higher in the LNME compared to the TME, with both having mixed or tumour-promoting effects in terms of cancer progression." (PMID 34439160, 2021). "PD-L1 expression in tumor cells is induced by a variety of growth factors including INF-γ, IL-1α and IL-27." (PMID 34299131, 2021). "Here, the authors propose an IL-27-independent tumor suppressor role for WSX1 in hepatocytes, showing that WSX1 restricts tumor progression by down-regulating PD-L1 expression in tumour cells and maximizing T cell mediated antitumor immune responses." (PMID 34108491, 2021). "Antigen-presenting cells stimulated by tumor antigens and CD40 can secrete IL-27, which has a dual function in regulating immune responses against cancer." (PMID 33418929, 2021). "Increased IL-27 levels predicted recurrence and DSS, especially among patients with a tumor diameter > 7 cm." (PMID 32621022, 2021).
tumor (continued). "Indeed, we recently reported that systemic delivery of IL-27 using rAAV could inhibit tumor growth and significantly enhance cancer immunotherapy in a variety of mouse tumor models without causing significant toxicity." (PMID 32292786, 2020). "Since these data suggested an involvement of IL-27 signaling in the anti-tumor efficacy of chemoimmunotherapy and flow cytometry analysis revealed enhanced NK cells frequencies upon this combinatorial treatment, we wondered whether IL-27 would directly affect NK cell cytotoxicity." (PMID 33014872, 2020). "Here, we show for the first time that tumor cells, such as the EOC cell lines SKOV3 and OVCAR5 and the primary cells A161, can express and release GBP1, but only after IL-27 or IFN-γ stimulation." (PMID 32093058, 2020). "Further lasso regression analysis identified seven potential prognostic markers (IL27, CD1D, NCOA6, CTSE, FCGRT, CFHR1, and APOA2) of robustness, most of which are related to tumor development." (PMID 32518711, 2020). "Similar to our findings in tumor cell lines, IFN-g preferentially activated STAT1 in Monos, while IL-27 activated both STAT1 and STAT3; IL-10 preferentially activated STAT3." (PMID 31730010, 2019). "The addition of IL-27 can promote CXCL10 production by MDSCs, resulting in the recruitment of anti-tumor NK and NKT cells reducing tumor size." (PMID 31681561, 2019). "To study whether this was linked to IL-27-signaling in macrophages, we generated BMDM from WT and IL27Rα KO mice and induced classical activation with LPS/IFNγ, alternative activation with IL-4, or directly co-cultured them with PyMT cells to induce tumor-like conditions." (PMID 31637217, 2019). "IL-27 also inhibits the development and function of Treg cells, which suppress T cell activation in the TME permitting tumor cell escape." (PMID 31681561, 2019). "This concept is further supported by work in EBI3 and IL-27R KO mice demonstrating that IL-27 directly enhances Treg activity by inducing CD39 expression, resulting in tumor growth." (PMID 31681561, 2019). "IL-27 enhances the development, proliferation, and cytotoxic activity of CD8+ T cells, thereby indirectly promoting anti-tumor immunity." (PMID 31681561, 2019). "Among the potential target genes of miRNA-328-5p, the DAB2IP, NFIC, IL-27, and HIC1 genes were tumor suppressors." (PMID 31776329, 2019). "Thus, IL-27 may serve to decrease fibroblast proliferation, while re-educating these cells to produce cytokines/chemokines and trigger an unfavorable environment for tumor cells." (PMID 31681561, 2019). "Taken together, IL-27 has important implications in the development of an anti-tumor T cell response by enhancing CTL activation, promoting Th1 mediated anti-tumor immune responses, and inhibiting Th2 and Treg mediated immune suppression." (PMID 31681561, 2019). "Among other TME-resident cytokines detected in human PD-L1+ tumor biopsies by GEP, IL-27 and IL- 1a increased PD-L1 expression on cultured tumor lines, alone or in combination with IFN-g." (PMID 30400822, 2018). "We tested also surface PD-L1 molecule, which is inducible by both IL-27 and IFN-γ, in different tumor cell types." (PMID 29020964, 2017). "Therefore, the effects of IL-27 on mouse NK cells might be tumor-type dependent." (PMID 28154569, 2017). "The retarded tumor growth in Zfp36−/− mice was recovered in the TTP and WSX-1 double knockout mice, further suggesting that IL-27-dependent antitumor effect is mediated by CD8 T-cells in Zfp36−/− mice." (PMID 29021521, 2017). "Another highly downregulated protein by IL27 was tropomyosin 1 (TPM1), which is known as a tumour suppressor." (PMID 26663990, 2015). "The model involves a dynamic network which includes tumor cells, CD8+ T cells and cytokines Interleukin-27, Interleukin-10 and Interferon-." (PMID 24633175, 2014). "IL-27 promotes the secretion of IL-10 and IFN- by CD4+ T cells, and we assume that these cytokines have the same effect on tumor rejection as those secreted by CD8+ T cells." (PMID 24633175, 2014).
tumor (continued). "Second, in mice, administration of an IL-27 expression plasmid resulted in an adjuvant activity for in vivo generation of Ag-specific CTL and in improved tumor eradication." (PMID 24130734, 2013). "Interleukin-27 signaling is mediated by the JAK-STAT pathway via activation of STAT1 and STAT3, which have tumor suppressive and oncogenic activities, respectively." (PMID 24274066, 2013). "Since IL-27 receptor is expressed predominantly on leukocytes and since IL-27 signaling is intact on the WT MMEC tumor tissue, enhanced tumor growth in Il27ra−/− mice can be attributed to reduced effectiveness of the anti-tumor immune response." (PMID 23554861, 2013). "This inhibiting effect was ascribed to an effect of IL-27 on various immune cells including CD8+ T cells, CD4+ T cells or NK cells, an anti-angiogenic effect, or direct suppressive effects on tumor cells." (PMID 24130734, 2013). "Recently, we have found that WSX1 is also expressed in multiple types of tumor cell lines and that WSX1 has an important role not only in immune cells but also in cancers of epithelial origin via an IL27-signaling-independent pathway." (PMID 21559505, 2011). "Elevated levels of pro-inflammatory cytokines, including TNF-α, IL-6, and IL-27, were detected in ALL patients, reflecting abnormal immune activation and suggesting a potential role in disease progression through tumor growth, immune evasion, or enhanced cytotoxicity." (PMID 41254398, 2025). "Given the widespread expression of IL-27R on both immune and non-immune cells, as well as IL-27’s dual effects on tumor cells, further research is needed to unveil its role in cancer patients." (PMID 40254608, 2025). "IL-27, produced by activated antigen-presenting cells like macrophages and dendritic cells, can activate natural killer (NK) cells and CD8 + T cells, enhancing their cytotoxicity against tumor cells." (PMID 41254398, 2025). "Here, we armed our VV with IL-27 and the results show that arming with IL-27 further enhances the antitumor effect of VVL-TD-RFP, leading to 100% tumor clearance and a long-term specific antitumor immune response in the DT6606 subcutaneous tumor model." (PMID 40350204, 2025). "In this study, we aimed to investigate whether IL-27 stimulation affects the expression of immune checkpoint molecules TIM-3 and Gal-9, thereby elucidating its potential anti-tumour role in CLL." (PMID 41296385, 2025). "We show here that COX2 expression at the tumor margin limits CD8+ T-cell infiltration into the tumor core, which involves at least in part reduced cytokine and chemokine expression (IRF8, CLEC9a, CXCL9, CXCL10, CXCL11, and IL27) that promotes directional immune cell migration." (PMID 39356141, 2024). "In apoptotic tumor cell condition medium (ACM)-treated moDCs, IL-27 expression was upregulated." (PMID 38566992, 2024). "We found that IL12, IL27, and IFNγ, which could increase the STAT1 expression to induce Th1 response in the tumor microenvironment, could also induce high expression of IFITM3 of Treg cells." (PMID 38167862, 2024). "Additionally, activated Treg cells can produce cytokines such as IL-35 and IL-27, which drive the expression of PD1 and TIM3, thereby creating a profoundly suppressive tumor immune microenvironment." (PMID 37828574, 2023). "While cabo monotherapy inhibited tumor growth and extended survival, IL-27 monotherapy did not demonstrate these therapeutic effects." (PMID 37842640, 2023). "Therefore, future research should investigate how a prophylactic vaccine consisting of tumor cells exposed to a method of ICD and IL-27 affects T cell (effector and memory) and NK cell responses." (PMID 35529885, 2022). "Taken together, the result supported the anti-tumor action of extracellular Hsp90ab1, and not Hsp90aa1, in regulating Lrp5, Runx2, TGFβ, and IL27 in tumor cells." (PMID 34830748, 2021).